CRP (C-reactive protein)
Diseases named in the same sentence as CRP in open-access papers (continued):
Sharing a sentence is not in itself a finding about the gene and the disease.
lung cancer (continued). "The association between elevated levels of inflammatory markers (such as C-reactive protein, interleukin-1 and interleukin-6) and psychological distress have been well documented, and these markers are linked with an increased risk of lung cancer." (PMID 37519799, 2023). "Elevated CRP levels in TB patients have been indicated as a risk factor for lung cancer." (PMID 37510958, 2023). "CRP is regarded as a classical inflammatory biomarker in oncology studies, and its level is correlated with malignant progression and treatment-associated complications in lung cancer patients." (PMID 37964929, 2023). "In their study, a 1 mg/L increase in C-reactive protein (CRP) among 7178 patients with stable cardiovascular diseases was associated with an increased incidence of new cancer (HR 1.07, 95%CI 1.04–1.09), particularly for lung cancer (HR 1.16, 95%CI 1.10–1.22)." (PMID 37508329, 2023). "Given the association between chronic inflammatory states and lung cancer, and the role of IL-1β as an upstream activator of a wide range of inflammatory cytokines and tumorigenesis, CRP may serve as a potential predictive biomarker of response." (PMID 37511306, 2023). "This study found that the elevation of D‐dimer, CRP, and NC may all play a role in the outcomes of patients with lung cancer‐associated acute ischemic stroke." (PMID 36065806, 2022). "Furthermore, C-reactive protein (CRP) is synthesized mainly as a result of stimulation by proinflammatory cytokines, and higher lung cancer risk and tumor progression are associated with elevated CRP levels." (PMID 36077992, 2022). "Given the current controversy concerning the efficacy of omega 3 supplements at reducing inflammation, we evaluated the safety and efficacy of omega 3 on reducing inflammation in people with a 6-year lung cancer risk >1.5% and a C reactive protein (CRP) level >2 mg/L in a phase IIa cross-over study." (PMID 36532545, 2022). "CRP is one of the inflammatory markers that cancer patients focus on, and high CRP levels may be associated with poor prognosis in lung cancer patients." (PMID 35910071, 2022). "In a randomized controlled trial of an anti-IL-1β monoclonal antibody (CANTOS study), originally designed as a secondary prevention trial to reduce cardiovascular events, serum CRP and IL-6 were found to be associated with lung cancer incidence and with time to cancer diagnosis." (PMID 35406394, 2022). "In a previous pilot study in patients undergoing pneumonectomy for lung cancer, we showed that underweight was associated with higher C-Reactive Protein (CRP) levels; we also found that systemic inflammation is associated with a lower plasmatic concentration of both albumin and prealbumin." (PMID 34572801, 2021). "We examined whether the mdNLR, methylation-derived immune cell ratios, and CRP Scores were associated with risk of dying of lung cancer among lung cancer cases." (PMID 34915912, 2021). "Elevated levels of CRP have been associated with increased lung cancer risk and tumor progression." (PMID 33925400, 2021). "Elevated CRP levels, elevated serum levels of pro-inflammatory cytokines, increased neutrophil counts and decreased lymphocyte counts, and polymorphisms in inflammation-related genes have been associated with increased lung cancer risk." (PMID 34915912, 2021). "For instance, C-reactive protein (CRP) is negatively associated with lung cancer outcome." (PMID 31487965, 2019). "Interestingly, this association was independent from CRP and 8-isoprostane levels, which suggests that the pathway from NO to lung cancer is independent from the inflammatory and oxidative stress processes that are reflected by these biomarkers." (PMID 31565153, 2019). "Indeed, the pattern of decline in CRP in relation to time since stopping smoking mirrors the risk curves observed for lung cancer incidence or total respiratory diseases and COPD mortality." (PMID 30150729, 2018).
lung cancer (continued). "Interestingly, PDA-associated HNF1A SNPs rs7310409, rs1169300, and rs2464196 are also associated with both an elevated risk (1.5–2 fold) of developing lung cancer and elevated circulating C-reactive protein (CRP)." (PMID 30074477, 2018). "Furthermore, CRP has been noted as a marker of lung cancer risk and interestingly, as a predictor of response to anti-EGFR gefitinib therapy." (PMID 28402963, 2017). "We therefore investigated whether the association with survival of the IL-6 plus IL-17A classifier and the IL-6, CRP and IL-17A classifier was specifically associated with survival in stage IA lung cancer patients." (PMID 28402963, 2017). "Among six genome-wide association (GWA) studies-identified lung cancer susceptibility loci assessed, a variant (rs2808630) of the C-reactive protein gene modified the associations for the “fruits and vegetables” (P for interaction = 0.03) and “American/Western” (P for interaction = 0.02) patterns." (PMID 27230571, 2016). "With CRP greater than 10 mg/L, lung cancer risk increased by 54% in this cohort." (PMID 27805040, 2016). "Thus, because of the non-specific nature of circulating CRP levels Hemelrijick and colleagues measured multiple time points of CRP and observed that this increased confidence in the link between elevation of CRP and lung cancer risk." (PMID 26425690, 2015). "Statistical analysis of clinical data between the low- and high-level groups of lung cancer patients revealed that the serum levels of CRP-SAA were closely associated with sex, smoking status, tumor size, lymph node involvement, distant metastasis, and clinical stage." (PMID 26264146, 2015). "The association between CRP and lung cancer has been widely investigated." (PMID 25996920, 2015). "In a large prospective study an elevated CRP level increased the risk of lung cancer." (PMID 26220864, 2015). "Elevated CRP-SAA levels were significantly associated with severe clinical features of lung cancer." (PMID 26264146, 2015). "Serum samples from two independent cohorts with lung cancer (retrospective cohort, 242 patients; prospective cohort, 222 patients) and healthy controls (159 subjects) were used to evaluate the prognostic value of CRP-SAA by enzyme-linked immunosorbent assay." (PMID 26264146, 2015). "CRP has long been associated with lung cancer risk and prognosis." (PMID 25114662, 2014). "It has been reported that an elevated resting energy expenditure in patients with various advanced cancers, such as pancreatic cancer and lung cancer, is associated with the presence of a systemic inflammatory response, as evidenced by an elevated CRP concentration." (PMID 24130817, 2013). "However, the reasons for these differential associations of CRP levels across lung cancer histologies are unclear and warrant further investigation." (PMID 22912790, 2012). "More work is needed to further investigate the associations of CRP across lung cancer histologies." (PMID 22912790, 2012). "In conclusion, we have demonstrated that elevated YKL-40 levels are associated with increased risk of gastrointestinal cancer, independently of CRP levels and that elevated CRP levels are associated with increased risk of lung cancer, independently of YKL-40 levels." (PMID 22095223, 2012). "Summary risk estimates of the association between ln CRP and lung cancer risk." (PMID 22912790, 2012). "Our meta-analysis has assessed the relation between CRP, IL-6 and lung cancer risk." (PMID 22912790, 2012). "CRP was associated with increased risk of lung cancer, especially among men." (PMID 22912790, 2012). "Lung cancer risk was particularly elevated in individuals with weight loss (OR 3.43, 95%CI 2.26–4.79), smoking (OR 3.24, 95%CI 2.76–3.83), haemoptysis (OR 3.18, 95%CI 1.33–5.60), elevated CRP (OR 3.02, 95%CI 2.30–3.84) and loss of appetite (OR 2.88, 95%CI 1.36–4.96)." (PMID 41379769, 2025).
lung cancer (continued). "Similarly, other researchers have proposed CRP thresholds on day 3 or day 4 (ranging roughly 150–220 mg/L) that can alert clinicians to a high risk of infectious complications, such as pneumonia or surgical site infection, following lung cancer surgery." (PMID 41153812, 2025). "Furthermore, we only revealed a preliminary correlation among lung cancer intestinal microbiota, metabolites, and proteomics, but the causal relationship among P. copri‐nervonic acid and all‐trans‐retinoic acid‐CRP, LBP, and CD14 axis needs further investigations." (PMID 35735103, 2022). "Therefore, CRP should be associated with non-lung cancer death as well as lung cancer death." (PMID 34350956, 2021). "While smoking is by far the most important risk factor for lung cancer, our DNA methylation-based CRP Scores provide the opportunity to examine inflammatory measures not related to smoking that could play a role in modulating cancer risk years prior to diagnosis." (PMID 34915912, 2021). "Patients in group A (hs-CRP<1 mg/L) were used as control group, and the results of multivariate Cox proportional risk regression model analysis showed that the incidence rates of lung cancer in patients in group B and C were 1.37 and 1.69 times as high as that in patients in group A, respectively." (PMID 31497547, 2019). "Thus, the association between elevated CRP levels and risk of lung cancer could represent confounding by pulmonary inflammation or reverse causation by occult lung cancer." (PMID 22095223, 2012). "have demonstrated the prognostic utility of CLR and similar CRP-based ratios in lung cancer patients receiving immunotherapy or chemotherapy, linking their elevation to an immunosuppressive state." (PMID 41451214, 2025). "Clinical trials demonstrate safety and efficacy with EPA (1.6 g) + DHA (0.8 g) daily for 12 weeks in lung cancer patients, showing improved nutritional status and suppressed inflammatory markers (CRP, TNF-α, IL-6)." (PMID 40808836, 2025). "These key features included activities of daily living (ADL), alkaline phosphatase, oxygen saturation, lactate dehydrogenase, non-lung cancer, respiratory rate, blood urea nitrogen, pulse rate, C-reactive protein, albumin, and systolic blood pressure." (PMID 40777144, 2025). "Several other systemic inflammation markers, such as the platelet-to-lymphocyte ratio (PLR), C-reactive protein (CRP), D-dimer, and lactate dehydrogenase (LDH), have been linked to prognosis in lung cancer and other solid tumors." (PMID 40941007, 2025). "We observe that in each fold the single latent variable correlates relatively strongly with four known markers for lung cancer, namely CRP, CYFRA 21 1, leukocytes, and hemoglobin." (PMID 40129053, 2025). "In lung cancer, arterial oxygen saturation had the highest MI for most patients, but for patients with short survival, protein expression, CRP and ECOG PS became even more critical." (PMID 39885364, 2025). "The present study aimed to evaluate the ability of a laboratory cachexia score (LCAS) defined by LDH, CRP and albumin, to identify cachexia and predict outcome in advanced lung cancer." (PMID 40133911, 2025). "Another important factor that indicates an amelioration in body composition and inflammation status is the reduction of albumin, CRP, and triglycerides levels, indicating a remodulation of the microenvironment of lung cancer." (PMID 39652453, 2025). "Among the inflammatory indices, C-reactive protein/albumin ratio (p=0.002), advanced lung cancer inflammation index (p=0.04), and neutrophil/lymphocyte ratio (p=0.008) were associated with overall survival." (PMID 40465984, 2025). "The only related work, a prospective study of lung cancer patients followed for 24 months, integrated D-dimer and CRP into a broader biomarker model that also included the lymphocyte-to-monocyte ratio to predict DP and mortality." (PMID 40563583, 2025).
lung cancer (continued). "Recent studies showed that baseline CRP and IL-6 levels predicted depressive symptoms during chemotherapy in a prospective cohort of lung cancer patients." (PMID 41149069, 2025). "It was reported that CRP levels were significantly higher in patients with lung cancer compared to healthy individuals." (PMID 40125102, 2025). "In these studies, YKL-40 was a stronger prognostic marker for gastrointestinal cancers, while CRP showed better prognostic ability for lung cancer." (PMID 40188292, 2025). "Substantial correlation was found among psychological factors, cognitive impairment, and CRP concentration in patients with advanced lung cancer." (PMID 40966684, 2025). "Patients (n = 261) with serum LDH, CRP and albumin measurement receiving palliative radiotherapy for advanced lung cancer between 2009 and 2015 were identified." (PMID 40133911, 2025). "This distribution of our lung cancer subgroups led to a higher CRP level predictive value for infection in the SCLC group." (PMID 40125102, 2025). "Some of these variables include C-reactive protein (CRP), ratio of neutrophils to lymphocytes (NLR), geriatric nutritional risk index (GNRI), and advanced lung cancer inflammation index (ALI)." (PMID 40282466, 2025). "Analysis indicated that CRP, albumin, total cholesterol, and cancer staging were primarily associated with CRA incidence in lung cancer patients with normal serum iron levels (p < 0.05)." (PMID 38562035, 2024). "The results show that CRA in lung cancer is mainly related to serum iron, CRP, albumin, total cholesterol, KPS score, surgery, and chemotherapy (p < 0.05)." (PMID 38562035, 2024). "The study revealed that PTH, CRP, IL-6, and lipid profile parameters play a significant role as markers of lung cancer progression." (PMID 39816276, 2024). "The findings of this study further demonstrate that CRP is a significant influencing factor for CRA in patients with normal serum iron in lung cancer, which means that the inflammatory state represented by CRP can affect CRA." (PMID 38562035, 2024). "The research on the relationship between CRP and the incidence of cancer, including colon cancer, BC, lung cancer, etc., has been widely studied." (PMID 38263420, 2024). "The primary objective of this study was to evaluate and compare the serum levels of PTH, CRP, lipid profile parameters, and IL-6 across different stages of lung cancer." (PMID 39816276, 2024). "CRA in lung cancer patients with decreased serum iron is primarily associated with albumin, age, and cancer staging, while CRA in lung cancer patients with normal serum iron is mainly related to CRP, albumin, total cholesterol, and cancer staging." (PMID 38562035, 2024). "Glasgow Prognostic Score (GPS) is an index that combines serum CRP and serum Alb levels, and it is a known prognostic factor for nonsmall cell lung cancer." (PMID 37747688, 2024). "Previous studies have linked elevated levels of C-reactive protein, IL-6, IFN-γ, and IL-1β to an increased risk of lung cancer." (PMID 39015494, 2024). "Previous studies have shown that CRP levels in patients with lung cancer are negatively correlated with serum iron levels." (PMID 38562035, 2024). "In the logistic regression analysis of lung cancer occurrence, some FFAs exhibited significant interaction effects with levels of C-reactive protein and lymphocyte counts." (PMID 39275200, 2024). "We measured circulating concentrations of neopterin, CRP, tryptophan and seven kynurenines in 5314 controls from 20 cohorts in the Lung Cancer Cohort Consortium (LC3)." (PMID 36653422, 2023). "In conclusion, HFD-induced CRP promotes lung cancer progression by modulating the immune response and enhancing cancer cell tumorigenicity." (PMID 37929799, 2023). "We further addressed the potential cellular origin of CRP for lung cancer progression by performing qPCR analysis to evaluate mRNA expression levels in the liver and adipose tissues." (PMID 37929799, 2023).
lung cancer (continued). "Nevertheless, a study found that notably high CRP in conjunction with at least one symptom was correlated with a greater than fourfold higher odd of lung cancer." (PMID 37873776, 2023). "A detailed analysis for different diagnoses showed that in patients with lung cancer, the covariates “CRP value,” “days from first diagnosis to randomization” as well as “gender” were significantly associated with survival time." (PMID 36937336, 2023). "CRP-SAA levels were found to be higher in lung cancer patients in one study, with a link between elevation and more severe characteristics, as well as lower overall survival rates." (PMID 37444523, 2023). "Our results imply that an HFD can turn the tumor growth environment into an immune-related pro-tumorigenic microenvironment and demonstrate that CRP has a role in promoting lung cancer development in this microenvironment." (PMID 37929799, 2023). "Previous studies have shown that NaHS can inhibit LPS-induced injury in A549 lung cancer cells by increasing cell viability, transmembrane electrical impedance, and expression of occluded small-band proteins and decreasing CRP levels." (PMID 38106638, 2023). "The present study has provided insight into the connection between HFD, CRP and lung cancer progression." (PMID 37929799, 2023). "Several studies identified that high CRP levels were risk factors for the development of lung cancer and elevated serum CRP levels will increase the incidence of lung cancer in male TB patients." (PMID 37817103, 2023). "High baseline levels of CRP and IL-6 trended toward shorter median time to lung cancer diagnosis, suggesting that IL-1β-inducible CRP and IL-6, similar to ctDNA at baseline, correlate positively with a more rapid progression to lung cancer diagnosis." (PMID 36074553, 2022). "High CRP level is observed in case of not only lung cancer and end-stage tumors but also infection, inflammation, trauma, tissue injury, and stress." (PMID 36684183, 2022). "Forced expiratory volume in the first second (FEV1) and C-reactive protein (CRP) significantly predict mortality from lung cancer with hazard ratio (HR) = 2.13 for FEV1 < 90% and HR = 3.38 for CRP > 2 mg/dl." (PMID 36046848, 2022). "Another Chinese clinic study in Hangzhou found that elevated serum CRP levels will increase the incidence of lung cancer in male tuberculosis patients." (PMID 35525982, 2022). "In particular, CRP is positively correlated with the abundance of gut bacteria in lung cancer patients, indicating that the elevated level of inflammatory components in peripheral blood may serve as a risk indication for lung cancer-mediated bacterial dysbiosis." (PMID 36358812, 2022). "In this randomized cross-over clinical trial with participants in a lung cancer screening study with CRP levels >2 mg/L, omega 3 significantly lowered CRP levels (by 23%) after 6 months of supplementation compared to their pre-treatment levels." (PMID 36532545, 2022). "This reduction in CRP is close to that achieved by Canakinumab in patients with cardiovascular disease, who also had a significantly lowered incidence of lung cancer in a secondary analysis." (PMID 36532545, 2022). "The modified Glasgow prognostic score (mGPS), a representative maker based on CRP and albumin, has been shown to be a prognostic indicator for various types of cancer, including lung cancer." (PMID 33866376, 2021). "A series of 1750 operable lung cancer patients who underwent complete resection proved that CRP levels at baseline and 3 days after surgery predict mortality." (PMID 33628809, 2021). "Serum total SOD activity and SOD1, SOD2, albumin, CRP, and ceruloplasmin concentrations were determined in lung cancer patients (n = 190) and control subjects (n = 52)." (PMID 34832849, 2021). "The cumulative incidence of lung cancer death tended to be higher in the high CRP group than in the low CRP group (Gray’s test p = 0.070)." (PMID 34350956, 2021).